FAM220A (family with sequence similarity 220 member A)
Description:
Promotes dephosphorylation of transcriptional activator STAT3 by interacting with both STAT3 and protein phosphatase PTPN2. This promotes interaction of PTPN2 with STAT3 and mediates STAT3 dephosphorylation by PTPN2, leading to negative regulation of STAT3 transcriptional activator activity. May be required for spermiogenesis or sperm function.
Synonyms: C7orf70; SIPAR; MGC12966; ACPIN1
Tractability: No criterion of Open Targets' tractability assessment is met for any kind of drug.
Gene: Protein-coding gene on chromosome 7 (6,329,411 to 6,348,981, reverse strand). Ensembl gene ENSG00000178397.
Subcellular location: Nucleus; Cytoplasm; Cytoplasmic vesicle, secretory vesicle, acrosome
Subcellular location (Human Protein Atlas): Vesicles
Gene Ontology:
Molecular function: protein binding
Cellular component: acrosomal vesicle; cytoplasm; nucleus
Genetic constraint (gnomAD): Loss-of-function variants: 1 observed, 0.77 expected, observed/expected ratio (o/e) 1.3, 90% interval 0.3 to 1.91. That is too few expected variants to judge how well the gene tolerates losing a copy. Missense variants: 392 observed, 331.45 expected, observed/expected ratio (o/e) 1.18, 90% interval 1.09 to 1.29. Synonymous variants: 141 observed, 135.26 expected, observed/expected ratio (o/e) 1.04, 90% interval 0.91 to 1.2.
Homologues: Orthologues: chimpanzee FAM220A (97% identical), macaque FAM220A (89% identical), dog FAM220A (54% identical), rat Fam220a (46% identical), mouse Fam220a (41% identical).
Diseases named in the same sentence as FAM220A in open-access papers:
FAM220A is named in the same sentence as 2 diseases in open-access papers, as found by Europe PMC text mining. Sharing a sentence is not in itself a finding about the gene and the disease. The quoted sentences say what the papers report.
Hypercholesterolemia (1 paper, 2021). An increased concentration of cholesterol in the blood. "Fam220a genes have been identified as novel target genes for miR-489-3p and miR-92a-3p associated with renal injury and hypercholesterolemia." (PMID 35036173, 2021).
FAM220A also shares sentences with these, for which no sentence is quoted: melanoma (2 papers).